DMD (dystrophin)
Diseases named in the same sentence as DMD in open-access papers (continued):
Sharing a sentence is not in itself a finding about the gene and the disease.
Duchenne muscular dystrophy (continued). "The sarcoglycanopathies were discovered by biochemical analysis of dystrophin, with variants in the corresponding gene being the genetic cause of Duchenne muscular dystrophy (DMD) or Becker muscular dystrophy (BMD)." (PMID 36292638, 2022). "Complete loss of dystrophin function causes Duchenne muscular dystrophy (DMD), the most common and lethal X-linked myopathy, whereas a partial loss results in Becker MD, having a milder phenotype." (PMID 36097021, 2022). "Duchenne muscular dystrophy (DMD) is a fatal muscle-wasting disease, caused by mutations in the dystrophin gene, characterised by cycles of muscle degeneration, inflammation and regeneration." (PMID 36444978, 2022). "Duchenne muscular dystrophy (DMD) is a degenerative muscle disease, caused by a mutation of the dystrophin gene on the X chromosome." (PMID 35893733, 2022). "The most severe and common muscular dystrophy, Duchenne muscular dystrophy (DMD), is a serious progressive muscle disease caused by mutations in the DMD (dystrophin-encoding) gene." (PMID 36076995, 2022). "Duchenne muscular dystrophy (DMD) is an X-linked disease, caused by a mutant dystrophin gene, leading to muscle membrane instability, followed by muscle inflammation, infiltration of pro-inflammatory macrophages and fibrosis." (PMID 35455028, 2022). "Duchenne muscular dystrophy (DMD) is a genetic, X-linked, muscle-wasting disease caused by different types of mutations in the DMD gene, which mostly disrupt the open reading frame and thus lead to an absence of functional dystrophin protein." (PMID 36514350, 2022). "Similar treatments were made using split inteins in dual AVV1 vectors to replace the mutated dystrophin gene in Duchenne muscular dystrophy (DMD)." (PMID 35211511, 2022). "Duchenne muscular dystrophy (DMD), the most common form of childhood muscular dystrophy, is caused by mutations in the DMD gene, which encodes the protein dystrophin." (PMID 35865113, 2022). "Duchenne muscular dystrophy (DMD), a severe and progressive X-linked disease that is characterized by muscular dystrophy, is caused by mutations in the dystrophin gene and has a global prevalence of approximately 0.005% of male births." (PMID 36619896, 2022). "Duchenne muscular dystrophy (DMD) is a progressive muscle wasting disorder caused by a mutation in the dystrophin gene." (PMID 34668666, 2022). "Significant levels of Cx43 lateralization is also observed in mouse models of Duchenne muscular dystrophy (DMD) which is characterized by the loss of dystrophin that stabilizes the sarcolemma in myocytes." (PMID 36712244, 2022). "Duchenne muscular dystrophy (DMD) is an X-linked muscle disease caused by out-of-frame mutations in the dystrophin gene that results in the complete loss of dystrophin protein." (PMID 36258243, 2022). "Duchenne muscular dystrophy (DMD) is a neuromuscular disorder caused by mutations in the dystrophin gene that affect the expression of dystrophin protein." (PMID 35457088, 2022). "Duchenne muscular dystrophy (DMD) is an X-linked recessive dystrophin-associated neuromuscular disorder (MIM # 310200) occurring in 15.9 to 19.5 per 100,000 live male births." (PMID 36361862, 2022). "Duchenne muscular dystrophy (DMD) is a severe X-linked inherited myopathy characterised by the mutation of the dystrophin encoding gene named DMD." (PMID 36555721, 2022). "Duchenne muscular dystrophy (DMD) is a genetic disorder characterized by progressive muscle degeneration due to dystrophin gene mutations." (PMID 35557546, 2022). "In Duchenne muscular dystrophy (DMD), the ability of MuSCs to divide asymmetrically is impeded by loss of the dystrophin protein, which plays a role in establishing the cell polarity that is required for asymmetric division." (PMID 35165120, 2022). "For example, oxidative damage to skeletal muscle fibers can worsen the pathology of Duchenne muscular dystrophy (DMD), a disease caused by mutations in the structural protein, dystrophin." (PMID 36291188, 2022).
Duchenne muscular dystrophy (continued). "Duchenne muscular dystrophy (DMD) is the most severe and common form among childhood muscular dystrophies due to a mutation in the dystrophin gene (DMD)." (PMID 35448710, 2022). "Dystrophin is located on the p21 region of the X chromosome and codes the causative gene for Duchenne Muscular Dystrophy (DMD) and Becker Muscular Dystrophy (BMD)." (PMID 35457001, 2022). "Duchenne muscular dystrophy (DMD) is a lethal X-linked inherited neuromuscular disorder caused by mutations in the gene encoding dystrophin, a cytoskeletal protein normally expressed in both muscles and in the central nervous system (CNS)." (PMID 36293496, 2022). "Duchenne Muscular Dystrophy (DMD) is caused by mutations of the dystrophin gene, which leads to progressive muscle fiber damage and degeneration, resulting in cardiac or respiratory failure and ultimately premature death." (PMID 36084954, 2022). "Duchenne muscular dystrophy (DMD) is a congenital myopathy caused by mutations in the dystrophin gene." (PMID 35886926, 2022). "Duchenne muscular dystrophy (DMD) (OMIM #300377) is a severe neuromuscular disorder (NMD) caused by pathogenic variants in the dystrophin gene which lead to progressive muscle degeneration and weakness." (PMID 36245386, 2022). "Duchenne muscular dystrophy (DMD) is the most prevalent inherited myopathy affecting children, caused by genetic loss of the gene encoding the dystrophin protein." (PMID 36420212, 2022). "Duchenne Muscular Dystrophy (DMD), also referred to as dystrophinopathy, is a devastating X-linked disease caused by mutations in the dystrophin gene which affects 1 in 5,000 to 1 in 6,000 live male births." (PMID 35720684, 2022). "DMD deletions, duplications, and mutations cause Duchenne muscular dystrophy (DMD), Becker muscular dystrophy (BMD), or cardiomyopathy [OMIM #300377]." (PMID 35762097, 2022). "A model for Duchenne muscular dystrophy (DMD), consisting of animals carrying a null mutation in dystrophin in hlh-1(ts) background, showed similar behavior." (PMID 35733850, 2022). "Duchenne muscular dystrophy (DMD) is caused by mutations in the dystrophin gene and dilated cardiomyopathy (DCM) is a major cause of morbidity and mortality in DMD patients." (PMID 36077200, 2022). "Duchenne muscular dystrophy (DMD) is an X-linked recessive progressive muscle disease caused by mutations in the DMD gene encoding dystrophin." (PMID 36012442, 2022). "Duchenne muscular dystrophy (DMD) is an intractable genetic muscular disorder characterized by the loss of DYSTROPHIN." (PMID 35377913, 2022). "Duchenne muscular dystrophy (DMD) caused by DMD gene mutations is the most common childhood form of muscular dystrophy, with approximately 1 in 5,000 male births worldwide." (PMID 36312227, 2022). "Duchenne muscular dystrophy (DMD) is a lethal disorder with out of frame mutations in dystrophin gene which impairs the production of dystrophin protein responsible for muscle strength and contractility." (PMID 33679927, 2021). "The system has been successfully used for targeting the human papillomavirus (HPV) 18 oncogene E6, the dystrophin gene causing Duchenne muscular dystrophy (DMD) and the HIV co-receptor C–C chemokine receptor type 5 (CCR5)." (PMID 33449167, 2021). "One of the best studied mediators of this class of change is Duchenne muscular dystrophy (DMD), caused by mutations in the dystrophin gene, which encodes a molecule that acts to prevent contraction-mediated cell damage." (PMID 33408083, 2021). "Duchenne muscular dystrophy (DMD) is a severe X-linked recessive disease caused by mutations in the dystrophin gene." (PMID 34627382, 2021). "Duchenne muscular dystrophy (DMD) is an incurable disease, caused by the mutations in the DMD gene, encoding dystrophin, an actin-binding cytoskeletal protein." (PMID 34479633, 2021). "For example, nonsense mutations in the dystrophin-encoding DMD gene result in loss of functional protein resulting in Duchenne muscular dystrophy (DMD)." (PMID 34469537, 2021).
Duchenne muscular dystrophy (continued). "In skeletal muscle, the genetic disease Duchenne Muscular Dystrophy (DMD) is characterized by progressive muscle degeneration due to a mutation in the dystrophin gene." (PMID 33558315, 2021). "Myo10 immunoreactivity in regions of dystrophin-deficient skeletal muscle samples from (A) mdx mice and (B) Duchenne muscular dystrophy (DMD) patients that are undergoing active regeneration." (PMID 34519272, 2021). "Duchenne muscular dystrophy (DMD) is the most common of the muscular dystrophies and is caused by mutations in the dystrophin gene." (PMID 33923553, 2021). "Duchenne muscular dystrophy (DMD) is a lethal X-linked recessive disorder that is caused by loss-of-function variants in the dystrophin gene." (PMID 33564172, 2021). "Duchenne muscular dystrophy (DMD) is an X-linked condition caused by deficiency of functional dystrophin protein." (PMID 34790118, 2021). "Duchenne muscular dystrophy (DMD) is a debilitating muscular disorder caused by frame‐shifting mutations in the DMD gene." (PMID 33337582, 2021). "Duchenne muscular dystrophy (DMD), induced by mutations in the gene encoding for the intracellular protein dystrophin, is a severe X chromosome-linked illness characterized by progressive muscle weakness and degeneration." (PMID 33619211, 2021). "Perturbation of the PTEN-PI3K/Akt pathway triggers excessive autophagosome formation and subsequently reduced autophagic flux within dystrophin-deficient myoblasts where these findings are of importance to understand Duchenne Muscular Dystrophy (DMD) patients." (PMID 34706731, 2021). "Duchenne muscular dystrophy (DMD) is a disorder caused by deletions or mutations in the dystrophin gene, preventing the production of functional dystrophin protein in skeletal muscle fibers, the diaphragm and the heart." (PMID 34199845, 2021). "Duchenne muscular dystrophy (DMD) is caused by mutations leading to complete or near-complete dystrophin defects in the skeletal muscle, resulting in muscular fibro-fatty degeneration." (PMID 34071145, 2021). "Mutations in the DMD gene, encoding dystrophin, can cause Duchenne muscular dystrophy (DMD), characterized by muscle weakness, inflammation, and fibrosis." (PMID 34394183, 2021). "Duchenne muscular dystrophy (DMD) is caused by mutations of the gene that encodes the protein dystrophin." (PMID 33579366, 2021). "Mutations in the DMD gene that code for dystrophin lead to a group of disorders called the dystrophinopathies, of which the most prominent member is the fatal Duchenne muscular dystrophy (DMD)." (PMID 34884423, 2021). "Duchenne muscular dystrophy (DMD) is a fatal X-linked recessive disorder that affects approximately 1 in 5000 male births due to mutations in the dystrophin gene." (PMID 33716768, 2021). "Duchenne muscular dystrophy (DMD) is an X-linked condition caused by a deficiency of functional dystrophin protein." (PMID 34790118, 2021). "Duchenne muscular dystrophy (DMD), caused by mutations in the gene encoding dystrophin (DMD) on the X chromosome, is a fatal and the most common inherited neuromuscular disorder in childhood, affecting 1 in 3500 to 5000 live male births." (PMID 34516770, 2021). "Duchenne muscular dystrophy (DMD) is an inherited genetic disease caused by mutations in the DMD gene, leading to muscle fiber degeneration and loss of dystrophin in skeletal muscle." (PMID 33808773, 2021). "Remarkably, CRISPR-Gold corrected 5.4% of the mutated dystrophin gene in mdx mice (a transgenic mouse model for Duchenne muscular dystrophy) and restored protein expression in muscles, which renders it a very promising therapeutic approach for Duchenne muscular dystrophy treatment." (PMID 34199901, 2021). "Mutations in the DMD gene encoding dystrophin—a critical structural element in muscle cells—cause Duchenne muscular dystrophy (DMD), which is the most common fatal genetic disease." (PMID 33845891, 2021).
Duchenne muscular dystrophy (continued). "Duchenne muscular dystrophy (DMD) is a progressive neuromuscular disorder, that arises from mutations in the dystrophin gene and leads to the absence or severe deficiency of the dystrophin protein." (PMID 33561994, 2021). "Duchenne muscular dystrophy (DMD) is an X-linked recessive neuromuscular disorder caused by mutations in the dystrophin encoding DMD gene." (PMID 33389442, 2021). "Duchenne muscular dystrophy (DMD), caused by mutations in the dystrophin gene, is an X‐linked disease affecting male and rarely adult heterozygous females, resulting in death by the late 20s to early 30s." (PMID 33619882, 2021). "Pharmacological corticosteroid therapy is the standard of care in Duchenne Muscular Dystrophy (DMD), a progressive, genetically inherited neuromuscular diseases arising from mutations in the dystrophin gene." (PMID 33663533, 2021). "Loss of dystrophin as in Duchenne muscular dystrophy (DMD) causes progressive skeletal muscle weakness and cardiac dysfunction." (PMID 34884423, 2021). "Duchenne muscular dystrophy (DMD) is caused by the lack of expression of dystrophin, which forms part of the dystroglycan structural complex in the sarcolemma." (PMID 34017265, 2021). "Duchenne muscular dystrophy (DMD) is an X-linked, progressive, degenerative muscle disease caused by loss of dystrophin in muscle tissues." (PMID 33617542, 2021). "Duchenne muscular dystrophy (DMD) is a genetic disorder that results from deficiency of the dystrophin protein." (PMID 34685536, 2021). "Duchenne muscular dystrophy (DMD) is an X-linked recessive disorder characterized by progressive muscle degeneration and weakness due to mutations in the dystrophin gene." (PMID 33627403, 2021). "Duchenne muscular dystrophy (DMD) is the most common and severe form of muscular dystrophies caused by mutations in the dystrophin gene." (PMID 34680151, 2021). "Duchenne muscular dystrophy (DMD) is a severe and progressive, X-linked, neuromuscular disorder caused by mutations in the dystrophin gene." (PMID 34680483, 2021). "Duchenne muscular dystrophy (DMD) is an X-linked striated muscle degenerative disease resulting from loss-of-function mutations in the dystrophin gene." (PMID 33651713, 2021). "Antisense oligonucleotide (AO)‐mediated exon‐skipping therapies show promise in Duchenne muscular dystrophy (DMD), a devastating muscular disease caused by frame‐disrupting mutations in the DMD gene." (PMID 33337582, 2021). "As a link between cardiac involvement and Duchenne muscular dystrophy, it has been observed that X-linked dilated cardiomyopathy (a disease where the cardiac muscle has no dystrophin expression) is usually accompanied by normal levels of dystrophin expression in skeletal muscles." (PMID 34066119, 2021). "Duchenne muscular dystrophy (DMD) is an X-linked recessive disorder resulting from loss-of-function of dystrophin." (PMID 34063001, 2021). "Duchenne muscular dystrophy (DMD) is an X-linked recessive muscle wasting disease caused by mutations in the DMD gene, which encodes the large cytoskeletal protein dystrophin." (PMID 32360405, 2020). "Duchenne muscular dystrophy (DMD) is a highly common and fatal X-linked disorder caused by nonsense and frameshift mutations in the dystrophin (DMD) gene." (PMID 32572084, 2020). "Duchenne muscular dystrophy (DMD) is a lethal, X chromosome-linked muscle disease caused by mutations in the dystrophin (DMD) gene, which result in the loss or altered function of dystrophin protein." (PMID 32224496, 2020). "While disruption of the DGC complex is also a consequence in Duchenne muscular dystrophy (DMD), a disease that is caused by mutations in the dystrophin gene, presentation, and clinical manifestations of CMDs differ from DMD in many respects." (PMID 32116541, 2020). "Duchenne muscular dystrophy (DMD) is an X-linked, lethal muscle degenerative disease caused by loss of dystrophin protein." (PMID 32826942, 2020).
Duchenne muscular dystrophy (continued). "A severe form of DCM is associated with mutations in the DMD gene encoding dystrophin, which are the cause of Duchenne Muscular Dystrophy (DMD)." (PMID 32477154, 2020). "Most Duchenne muscular dystrophy (DMD) cases are caused by deletions or duplications of one or more exons that disrupt the reading frame of DMD mRNA." (PMID 32970732, 2020). "Duchenne muscular dystrophy (DMD) is an X-linked recessive disorder affecting the expression of dystrophin protein, an essential protein that maintains muscle fiber integrity and function." (PMID 33053810, 2020). "Duchenne muscular dystrophy (DMD) is a fatal X-linked disorder caused by nonsense or frameshift mutations in the DMD gene." (PMID 32572084, 2020). "Duchenne muscular dystrophy (DMD) is caused by loss of dystrophin in muscle, and while all patients share the primary gene and biochemical defect, there is considerable patient–patient variability in clinical symptoms." (PMID 32592467, 2020). "Duchenne muscular dystrophy (DMD) is a fatal progressive muscle wasting disease, caused by mutations in the DMD gene." (PMID 33051488, 2020). "Duchenne muscular dystrophy (DMD) is a deadly X-linked disease resulting from mutations in the dystrophin gene." (PMID 32664329, 2020). "Duchenne muscular dystrophy (DMD), one of the most common forms of muscular dystrophy, is caused by recessive mutations in the dystrophin gene on the X chromosome and affects 1 in 3500–5000 newborn males worldwide." (PMID 32992747, 2020). "Duchenne Muscular Dystrophy (DMD) is a lethal muscle disorder, caused by mutations in the DMD gene and affects approximately 1:5000–6000 male births." (PMID 32499563, 2020). "Duchenne muscular dystrophy (DMD) is a serious muscle-wasting disorder, caused by lack of dystrophin protein, which is essential for the normal functioning of the muscle cells, including muscle contraction and movement." (PMID 32244535, 2020). "Duchenne muscular dystrophy (DMD) is a genetic disorder associated with a progressive deficiency of dystrophin that leads to skeletal muscle degeneration." (PMID 32365922, 2020). "Duchenne muscular dystrophy (DMD) is an X-linked, lethal neuromuscular disorder caused by mutations in the dystrophin gene affecting 1 in approximately 5000 males at birth." (PMID 32070342, 2020). "Duchenne muscular dystrophy (DMD), the most common form of paediatric muscular dystrophy occurring in 1/3,500–5,000 boys, is caused by mutations in the DMD gene encoding dystrophin." (PMID 33210465, 2020). "Duchenne muscular dystrophy (DMD) is a fatal neuromuscular disorder generally caused by out-of-frame mutations in the DMD gene." (PMID 33238405, 2020). "Duchenne muscular dystrophy (DMD) is an X-linked progressive muscle wasting disease caused by a deficiency in dystrophin, leading to progressive myofiber necrosis, fibrosis and muscle weakness." (PMID 32341395, 2020). "Duchenne muscular dystrophy (DMD) is caused by mutations in the DMD gene that abolish the expression of dystrophin protein." (PMID 31961902, 2020). "Duchenne muscular dystrophy (DMD) is caused by mutations of the dystrophin gene, and is a quite common monogenic sex-linked human disease, whose incidence is approximately 1:5000 in newborn boys." (PMID 32189222, 2020). "In Duchenne muscular dystrophy (DMD), DYSTROPHIN deficiency exposes myofibers to repeated cycles of contraction/degeneration, ultimately leading to muscle loss and replacement by fibrotic tissue." (PMID 32359374, 2020). "Duchenne muscular dystrophy (DMD) is a fatal, X-linked recessive muscle disease caused by a spectrum of mutations in the DMD gene that result in the loss of dystrophin from sarcolemma." (PMID 32849198, 2020). "Duchenne muscular dystrophy (DMD) is the most common paediatric muscular dystrophy and is caused by mutations in the DYSTROPHIN gene." (PMID 32087527, 2020). "Duchenne muscular dystrophy (DMD) is a fatal muscle‐wasting disease arising from mutations in the dystrophin gene." (PMID 31755636, 2020).